INS (insulin)
Diseases named in the same sentence as INS in open-access papers (continued):
Sharing a sentence is not in itself a finding about the gene and the disease.
Insulin resistance (continued). "Interestingly, conventional insulin resistance indices, such as the Homeostasis Model Assessment of Insulin Resistance (HOMA-IR), and insulin sensitivity indices, such as the Quantitative Insulin Sensitivity Check Index (QUICKI), remained unchanged after 3 months of GLP-1 receptor agonist therapy." (PMID 40565353, 2025). "This non-significant increase could not translate into significant changes in fasting glucose, insulin, and insulin resistance, except in the group that underwent resistance endurance, which showed a significant reduction in fasting glucose." (PMID 40134450, 2025). "However, the existence of disproportionate insulin hypersecretion without detectable insulin resistance in lean PCOS patients (who do not have obesity as a confounding factor) challenges the mechanism of compensatory hyperinsulinemia." (PMID 40013621, 2025). "However, the absence of a corresponding increase in insulin levels supports the notion that α-cyclodextrin exerts its beneficial effects independently of insulin production, and thus, its efficacy is not impaired by insulin resistance." (PMID 40574064, 2025). "Although fasting insulin and HOMA-IR levels were also higher in the dysglycemic groups, this difference reached statistical significance only in the obese and morbidly obese groups, indicating that insulin resistance becomes more pronounced with increasing adiposity." (PMID 40951687, 2025). "Therefore, while an intrinsic molecular aberration has not been consistently associated with skeletal muscle insulin resistance in PCOS, it seems that physiological features of PCOS are able to instigate some reductions in insulin sensitivity in this tissue." (PMID 40013621, 2025). "Additionally, while in study cohorts only made of men serum AGEs were not linked with insulin resistance, in women dietary AGE restriction resulted in an improvement in insulin sensitivity." (PMID 40263184, 2025). "However, when compared to sedentary individuals, HSkMCs derived from habitual exercisers displayed enhanced insulin sensitivity (elevated insulin‐stimulated glycogen synthesis) but without additional protection from fatty acid‐induced insulin resistance." (PMID 41029907, 2025). "Next, insulin tolerance tests were performed, when glucose levels were evaluated within 30 min after an intraperitoneal injection of insulin, allowing us to calculate both the area under the curve (AUC0–30 min) and Kitt values, as an index of insulin resistance." (PMID 40722898, 2025). "Insulin resistance (IR) is a pathological condition in which insulin fails to promote glucose uptake in peripheral tissues, primarily the skeletal muscle and liver, despite adequate insulin secretion." (PMID 40699860, 2025). "Third, TyG index as an indicator for insulin resistance may not fully explain the complexity of insulin dysregulation." (PMID 40290665, 2025). "Therefore, treatments targeting insulin resistance (e.g., insulin or metformin) used in human PCOS are not directly translatable or effective in managing OFC in cows." (PMID 40725447, 2025). "Another SNP variation, SNP rs769214, was found to be significantly associated with insulin resistance, obesity, higher BMI Z-score, adipocyte fatty acid-binding protein (A-FABP) and with higher plasma insulin concentration, without any effect on erythrocyte CAT activity as well." (PMID 40428311, 2025). "Furthermore, the pooled analysis revealed a trend toward a reduction in homeostasis model–insulin resistance index (HOMA-IR) levels, suggesting that White Mulberry may improve insulin sensitivity." (PMID 40732887, 2025). "However, in this context, it should be noted that individuals with PWS have less insulin resistance and lower insulin levels compared to obese individuals without PWS." (PMID 40136445, 2025). "In addition, although the insulin therapy can control the blood glucose, it has no therapeutic impact on the function of β-cells and the insulin resistance." (PMID 41488874, 2025).
Insulin resistance (continued). "Although obesity, insulin resistance, and endogenous hyperinsulinemia are not prerequisites for T1D, its treatment involves exogenous subcutaneous insulin administration, leading to supraphysiological insulin concentrations in the systemic circulation." (PMID 40943118, 2025). "Furthermore, elevated fasting plasma glucose, increased circulating insulin levels, and a higher HOMA-IR index were observed in the HFD mice, indicating the presence of systemic insulin resistance." (PMID 40710585, 2025). "Clinical definitions of insulin resistance primarily concern the impacts of insulin on glucose homeostasis, while disregarding other insulin-mediated cellular processes that may or may not be functioning normally." (PMID 40013621, 2025). "This study confirms that CIHH enhances insulin utilization without significantly elevating insulin levels—an effect validated through the Homeostatic Model Assessment of Insulin Resistance (HOMA-IR), Homeoatic Model Assessment of Insulin Sensitivity (HOMA-IS), and insulin tolerance test (ITT)." (PMID 41295293, 2025). "However, mice where Irs2 is silenced, specifically in the liver, show selective insulin resistance, in which insulin no longer suppresses the process of gluconeogenesis but continues to activate lipogenesis." (PMID 40426854, 2025). "However, A-KO mice displayed significantly elevated fasting insulin levels and a 2-fold higher HOMA-IR (Homeostatic Model Assessment for Insulin Resistance) index, consistent with the whole-body insulin resistance with glucose uptake genes remaining largely unchanged in the liver." (PMID 40196683, 2025). "However, eGDR should be interpreted with caution because it relies on factors known to relate directly to insulin resistance and thereby does not allow independent assessment of insulin sensitivity or responsiveness." (PMID 39998445, 2025). "Thus, stopping the negative impact of oxidative stress on the insulin signaling pathway helps reverse insulin resistance and metabolic dysfunction." (PMID 39873298, 2025). "Similarly, HOMA-IR is ∼33% lower in the 0.2% BAM15 group suggesting that the increased insulin concentration was not secondary to increased insulin resistance relative to db/db control mice." (PMID 40639664, 2025). "Altogether, these findings suggest that dysregulated synthesis of insulin in the absence of glucose stimulus could lead to epigenetic alterations that may ultimately result in insulin resistance." (PMID 39471069, 2025). "In people with insulin resistance, insulin fails to effectively suppress the apolipoprotein C-III (ApoC-III), which is one of the most potent inhibitors of LPL, which inhibits LPL action in peripheral tissues and favors hepatic uptake of TG-rich chylomicron debris." (PMID 41441034, 2025). "Therefore, in the context of insulin therapy in T1DM, it may further raise leptin levels, dysregulate metabolic control, increase appetite, facilitate weight gain, and develop insulin resistance." (PMID 40277935, 2025). "Mechanistically, while insulin normally promotes bone formation by stimulating osteoblast proliferation and differentiation through the PI3K/Akt signaling pathway, this anabolic effect is significantly weakened in hyperglycemic conditions due to insulin resistance." (PMID 40529826, 2025). "The serum insulin levels (Cohen’s d = 0.95) and HOMA-IR (Cohen’s d = 0.98) of CON mice were significantly lower than the HFD group (p < 0.01), suggesting 12 weeks of high-fat diet feeding triggered weight gain, leading to lipid accumulation and insulin resistance in mice." (PMID 41002956, 2025). "Although selenium supplementation was associated with a substantial rise in the quantitative insulin sensitivity check index and TAC, it did not significantly lower FPG or the homeostatic model assessment of insulin resistance, according to this study’s detailed analysis." (PMID 41141267, 2025).
Insulin resistance (continued). "NAFLD disrupts glucose metabolism through several key mechanisms: Hepatic insulin resistance develops primarily through lipid accumulation-induced impairment of IRS phosphorylation, while concurrent mitochondrial dysfunction activates the ROS-JNK pathway, further disrupting insulin signaling." (PMID 40551893, 2025). "The extract of Salvia officinalis can significantly reduce insulin levels and the homeostasis model assessment of insulin resistance in PCOS patients, and significantly increase the quantitative insulin sensitivity check index, thus improving insulin resistance markers." (PMID 40842497, 2025). "While impairments in insulin signaling and GLUT4 translocation significantly contribute to disrupted glucose uptake in skeletal muscles in T2D, it is important to emphasize that mitochondrial dysfunction also plays a pivotal role in the pathophysiology of insulin resistance." (PMID 40944248, 2025). "Nevertheless, no direct link was identified between CDAI and insulin levels or insulin resistance." (PMID 40732969, 2025). "miR-222 promotes insulin resistance in skeletal muscles and the liver, and miRNA-27a downregulates PPAR-γ in skeletal muscle, inducing insulin resistance, whereas miR-141-3 promoted glucose uptake and boosted insulin sensitivity in liver via inhibition of PTEN." (PMID 40696355, 2025). "Notably, the absence of individuals with normal BMI in our insulin-resistant subgroup further accentuates the complex interrelation between obesity, insulin resistance, and inflammation in PCOS." (PMID 40226143, 2025). "Furthermore, a much lower daily 5 mg dose of resveratrol was found to reduce systolic blood pressure, HbA1c levels, and improve insulin sensitivity, while not affecting the homeostatic model assessment of insulin resistance, in a 28-day long treatment." (PMID 40943191, 2025). "Notably, recent reports suggest that lower insulin infusion rates are equally effective in treatment of HTG in individuals without insulin resistance." (PMID 40612706, 2025). "Other factors, such as increased glucose flux and metabolic stress associated with insulin resistance, may contribute to PKM2 upregulation independent of insulin therapy." (PMID 40136665, 2025). "In summary, the Energy Model of Insulin Resistance provides a framework for understanding that the primary metabolic deficit in people with insulin resistance may not be abnormal insulin signaling, but rather an abnormally increased metabolic demand for sugar." (PMID 40421040, 2025). "However, insulin concentrations (P = 0.058) and static markers of insulin resistance (homeostatic model assessment for insulin resistance [HOMA-IR] and adipose insulin resistance [AdipoIR], an index of adipose insulin sensitivity) still tended to be higher in the HighLF." (PMID 40309768, 2025). "Unlike IRS and Akt activation, which are components of the proximal canonical insulin signaling pathway, GLUT4 vesicle translocation to the plasma membrane does not exhibit the same ‘spareness’ as IRS and Akt activation and is therefore less debated on its importance during insulin resistance." (PMID 41305671, 2025). "As for type 1 diabetes, there is no clear-cut report of HbA1c reduction by periodontal treatment, and it is classically known that elevated inflammatory markers such as CRP are related to insulin resistance (HOMA-IR) rather than insulin secretion capacity (HOIMA-β)." (PMID 40070580, 2025). "Additionally, 2-month-old CB2R −/− mice on HFD exhibited reduced weight gain and maintained normal insulin sensitivity, while 12-month-old obese CB2R −/− mice did not develop insulin resistance and showed an enhanced insulin-stimulated glucose uptake." (PMID 39941074, 2025). "Several surrogate markers for insulin resistance have been established, among which the triglyceride-glucose (TyG) index stands out as a readily accessible and clinically promising alternative that does not require insulin measurement." (PMID 40458175, 2025).
Insulin resistance (continued). "In T1DM patients who maintain a healthy energy balance and exhibit no insulin resistance, insulin therapy may enhance vascular endothelial function, as selective insulin resistance is not a relevant factor." (PMID 40093018, 2025). "Hypothesizing that the plasma membrane protein, transient receptor potential ankyrin-1, is a pivotal target in insulin resistance, we investigated the mechanism of action of cinnamaldehyde (CIN), an electrophilic TRPA1 agonist, in skeletal muscle, a primary insulin target." (PMID 39861427, 2025). "Although insulin resistance was not measured directly, an increase in fasting insulin levels following regular coffee consumption may reflect a short-term reduction in insulin sensitivity." (PMID 40565007, 2025). "First, curcumin metabolites were reported to improve insulin sensitivity by activating the PI3K-AKT-GSK3B and AMPK signaling pathways and suppressing the phosphorylation of ERK/JNK, which are crucial in counteracting insulin resistance, in high-glucose-induced insulin-resistant HepG2 cells." (PMID 40563357, 2025). "Contrary to the study's hypothesis, fasting serum insulin [PBND = −0.0 mU/L(−0.8 to 0.8), MCRD = −1.3 mU/L (−2.4 to −0.3), p = 0.034] and insulin resistance [PBND = 0.03 (−0.24–0.18), MCRD = −0.37 (−0.68 to −0.06), p = 0.030] were improved significantly in the MCRD group." (PMID 40078500, 2025). "However, when insulin secretion does not adequately match the degree of insulin resistance, maternal blood glucose levels rise, potentially resulting in GDM." (PMID 40618386, 2025). "However, until surgery or if surgery is not feasible, the first choice ADD is metformin, an insulin sensitizer, aimed at improving the insulin resistance arising from the hypersecretion of counter-regulatory hormones." (PMID 40175622, 2025). "Similarly, studies have reported a significant reduction in insulin resistance (assessed by HOMA‐IR) and an increase in insulin sensitivity index (assessed by the predicted insulin sensitivity index: PREDIM) among overweight individuals adhering to a vegan diet low in PRAL and NEAP." (PMID 41378230, 2025). "Recent studies have revealed that CEMA, as an acrolein exposure biomarker, could decrease insulin sensitivity and raise fasting insulin FPI, FPG, HOMA-insulin resistance, risks of prevalent IR, impaired fasting glucose, impaired fasting glucose (IFG), and the risk of type 2 diabetes, respectively." (PMID 40190764, 2025). "Given this increase in insulin sensitivity, despite otherwise unchanged metabolic parameters, we next investigated whether conditional Pnoc deletion in B cells could mitigate the development of high-fat diet (HFD)-induced insulin resistance." (PMID 40662198, 2025). "Furthermore, catechins have also been proven to enhance insulin sensitivity and reduce its resistance when combined with coffee chlorogenic acids, as shown by a decreased homeostatic model assessment of insulin resistance index (HOMA-IR) and better postprandial insulin responses." (PMID 40563357, 2025). "The nature of insulin deficiency, whether absolute (the pancreas produces very little or no insulin) or relative (insulin is insufficient to overcome insulin resistance), distinctly influences bone microarchitecture and strength." (PMID 40564223, 2025). "Next, we assessed the SHAP values of metabolites in relation to several glucose and insulin indices in our cohorts, encompassing 2-h OGTT levels, fasting blood glucose (FBG), hemoglobin A1c (HbA1c), fasting insulin, homeostatic model assessment of insulin resistance (HOMA-IR) and FINDRISC." (PMID 40200054, 2025). "In MetS, insulin resistance (elevated HOMA-IR) and beta-cell dysfunction (elevated HOMA-B) are often present together since the initial response of the body to insulin resistance is often a compensatory elevation in systemic insulin levels, resulting in initially elevated HOMA-B." (PMID 40732915, 2025).
Insulin resistance (continued). "In adipose tissues of obese mice, impaired FGF21 signaling cascades led to a defect in the ability of FGF21 to induce GLUT1-dependent glucose uptake and ADP secretion, thereby resulting in insulin resistance, while FGF21 infusion could improve glucose uptake and insulin sensitivity in obese mice." (PMID 40756666, 2025). "Furthermore, we observed significant changes in various cardiometabolic parameters in both groups, such as reductions in insulin resistance (HOMA and QUICKI), systolic blood pressure, and insulin concentrations, along with increases in HDL cholesterol concentration." (PMID 40647247, 2025). "A key limitation concerns the assessment of glucose homeostasis, which, although addressed in some studies, did not include comprehensive parameters such as insulin resistance (HOMA-IR) or insulin sensitivity indices, thereby limiting a complete understanding of metabolic regulation." (PMID 40075613, 2025). "Similarly, a reduction in PPARG expression indicates insulin resistance, as PPARG is the main regulator of sensitivity to insulin, but also suggests disturbances in lipid homeostasis, which may lead to lipotoxicity." (PMID 40806527, 2025). "Whether the induction of c‐Fos by feeding in healthy, insulin‐sensitive mice, on a chow diet, is recapitulated in obese mice with steatosis and insulin resistance is not known." (PMID 41024433, 2025). "The impairment of the anti-lipolytic action of insulin leads to increased lipolysis in adipocytes and increased circulating FFA, resulting in large amounts of FFA being sent to the liver and new lipogenesis, which in turn leads to steatosis and insulin resistance in muscle cells." (PMID 40723862, 2025). "A ~50% reduction in the homeostatic model of assessment for insulin resistance (HOMA‐IR) with FA supplementation at both 5× and 10× doses was previously reported in our cohort, indicating improved systemic insulin sensitivity, which primarily reflects hepatic insulin action under fasting conditions." (PMID 41170010, 2025). "Together, these results highlight the role of REPS1 as a key signaling protein impaired in insulin resistance and suggest that enhancing REPS1 phosphorylation could be a potential therapeutic strategy to improve insulin sensitivity and restore glucose uptake in metabolic disorders such as T2D." (PMID 40482643, 2025). "Lastly, whilst it has previously been shown that cruciferous vegetable sprouts can improve fasting insulin and insulin resistance in participants with type 2 diabetes, we have not measured fasting insulin due to a lack of power and the cost of insulin measurements." (PMID 40375391, 2025). "On the other hand, in the context of hepatic insulin resistance, a typical pathway‐selective insulin responsiveness, insulin fails to suppress hepatic glucose production but stimulates lipogenesis, resulting in hyperglycaemia, hyperlipidaemia and hepatic steatosis." (PMID 40245241, 2025). "In insulin-resistant visceral adipose tissue, insulin fails to suppress lipolysis by increasing circulating FFAs, affecting hepatic and muscle metabolism and aggravating insulin resistance." (PMID 40362446, 2025). "However, whether overexpression of the Slc2a4 gene in RNF20 knockdown cells could alleviate insulin resistance remains to be investigated, which would better elucidate the role of RNF20 in insulin signalling via Slc2a4 regulation." (PMID 40522008, 2025). "Interestingly, Sema-treated mice had reduced homeostatic model assessment of insulin resistance (HOMA-IR), which suggests that these mice could have increased insulin sensitivity, a feature that could contribute to the flattened glucose response to OGTT." (PMID 41163813, 2025). "Given the observed enhancement in insulin sensitivity with IIR under relatively moderate exercise conditions, this approach warrants further investigation to determine its applicability and efficacy in populations with insulin resistance or limited exercise tolerance." (PMID 40892466, 2025).